PTH (parathyroid hormone)
Diseases named in the same sentence as PTH in open-access papers (continued):
Sharing a sentence is not in itself a finding about the gene and the disease.
hypophosphatemia (continued). "Among them, only one had hypophosphatemia and the other serum phosphorus levels at the lower limit, both with FGF23, αKlotho, 25OHD3 and PTH within the reference range." (PMID 40133996, 2025). "Following vitamin D supplementation, 25-hydroxyvitamin D levels increased modestly (13.3 ng/mL) but hypophosphatemia worsened (2.0 mg/dL), while ALP and PTH levels remained elevated." (PMID 41226894, 2025). "Laboratory analyses revealed hypophosphatemia with serum phosphate levels ranging from 0.42 to 0.55 mmol/L (normal range, 0.85- 1.51 mmol/L), ALP at 142 U/L (normal range, 30- 120 U/L), and PTH at 281.7 pg/mL (normal range, 15- 65 pg/mL)." (PMID 38887276, 2024). "The patientpresented here had hypophosphatemia and hyperphosphaturia (TmP/GFR) but intact FGF23,calcitriol, calcium, and PTH concentrations were all within the reported reference ranges." (PMID 38746050, 2024). "Following KT, high PTH and FGF-23 levels increase urinary phosphate excretion and result in hypophosphatemia as the graft function recovers." (PMID 37183797, 2023). "Hypophosphatemia arising from an intrinsic increase in FGF23 secretion is characterized by reduced phosphate reabsorption, low 1,25D, and high-normal PTH." (PMID 37635983, 2023). "In this regard, high PTH and FGF-23 levels are frequent after transplant and contribute to hypophosphatemia." (PMID 35602513, 2022). "This process is driven by parathyroid hormone (PTH) and other mediators, including hypophosphatemia, and growth hormone (GH)." (PMID 35353297, 2022). "High basal levels of PTH and FGF-23 make post-transplant hypophosphatemia and hypercalcemia a common finding." (PMID 35602513, 2022). "The first group with FGF23‐dependent hypophosphatemia (FDH)—having low TmP/GFR, high cFGF23, normal renal function, and normal or mild PTH elevation—was recruited to assess the effect of elevated cFGF23 upon TmP/GFR in the presence of variable PTH activity." (PMID 33615106, 2021). "Many factors are recognized as contributing to hypophosphatemia, mainly persistent high levels of FGF-23 and PTH and the influence of immunosuppressive drugs." (PMID 33909856, 2021). "Laboratory features were consistent with HR with hypophosphatemia, normocalcemia, high ALP, normal/normal- high PTH, and low TPR." (PMID 31514490, 2020). "Normalization of the serum PTH concentration will restore normal renal TRP, with consequent correction of hypophosphatemia." (PMID 32596195, 2020). "Phosphate is freely filtered at the glomerulus and then reabsorbed, but proximal tubular reabsorption is inhibited by both PTH and FGF‐23, resulting in hypophosphatemia." (PMID 31687644, 2019). "Hypophosphatemia, increased ALP level and urine phosphate excretion, normal calcium and PTH levels, and rachitic X-ray findings were found." (PMID 29505567, 2018). "Hypophosphatemia is also related to HCM, namely the decrease of renal reabsorption of phosphates, likely due to a PTH-rp-induced effect." (PMID 28977163, 2017). "In contrast, Fgfr1DT-cKO mice unexpectedly developed hypercalciuria, secondary elevations of parathyroid hormone (PTH), hypophosphatemia and enhanced urinary phosphate excretion." (PMID 26839958, 2016). "More research is needed to determine the relationships between PTH, FGF-23, and hypophosphatemia with TMV bone parameters, and to identify possible therapeutic targets." (PMID 24605319, 2014). "Persistent elevation of parathyroid hormone (PTH), sometimes autonomous, is well described, and hypophosphatemia owing to inappropriate urinary phosphate wasting with restoration of renal clearance is frequently seen in the early posttransplant period." (PMID 22811905, 2012). "At 5 years, laboratory tests to evaluate Ca2+ metabolism revealed hypercalciuria, normocalcemia, hypophosphatemia, hyperphosphaturia, elevated serum alkaline phosphatase (ALP) and parathyroid hormone (PTH) but with normal 25-hydroxy vitamin D3 and calcitriol levels." (PMID 38528055, 2024).
hypophosphatemia (continued). "Elevated PTH reduces proximal tubular reabsorption and increases urinary phosphorus excretion, while osteoclasts do not release bone phosphorus, leading to hypophosphatemia." (PMID 39287282, 2024). "While we have not measured intestinal Pi absorption in this model, it is possible that the residual increase in 1,25(OH)2D contributes to increased intestinal Pi absorption, which in turns contributes to the full correction of the hypophosphatemia despite residual increases in FGF23 and PTH." (PMID 37943605, 2023). "None of the patients reported here had overt hypophosphatemia, or abnormal circulating vitamin D or PTH levels." (PMID 36091358, 2022). "No participating woman had hypophosphatemia at baseline; moreover, all women had fractional excretion of phosphorus, plasma calcium, and plasma PTH within the physiological range." (PMID 32654663, 2020). "Because hypophosphatemia is the unifying basis for all forms of rickets, the general principle of VDDR management is to maintain the serum calcium level in the midnormal range to achieve a normal serum level of PTH." (PMID 32596195, 2020). "The results of our study challenge existing paradigms in mineral homeostasis; our data provide evidence that hypophosphatemia can develop in the absence of serum changes in the phosphaturic hormones, PTH and FGF-23 and despite declining serum Klotho levels." (PMID 32634148, 2020). "In patients with hypophosphatemia due to impaired phosphate reabsorption, high IP raised [PTH] without correcting [P]s." (PMID 28445401, 2017). "In addition to hypophosphatemia, decreased TRP, normal or mildly elevated serum levels of PTH and markedly elevated serum levels of ALP are typically detected." (PMID 29280738, 2017). "Moreover, the regulation of the major known phosphate regulating hormones, PTH, 1,25 Dihydroxycholecalciferol, FGF23 in response to hypophosphatemia was intact and suggests rather compensatory adaptation." (PMID 22859939, 2012). "However, our patient had a normal PTH level despite phosphate supplementation prior to treatment with burosumab, and our patient's hypophosphatemia resolved with burosumab without phosphate supplementation." (PMID 40922882, 2025). "Laboratory analyses revealed hypophosphatemia with serum phosphate levels ranging from 0.25 to 0.64 mmol/L (normal range, 0.85- 1.51 mmol/L), elevated ALP levels ranging from 173 to 257 U/L (normal range, 30- 120 U/L), and increased PTH at 104.8 pg/mL (normal range, 15- 65 pg/mL)." (PMID 38887276, 2024). "Additionally, individuals with hypophosphatemia exhibited higher levels of PTH compared with those with normal phosphate levels (5.0 vs 4.3 pmol/mL, P = .03)." (PMID 37985930, 2024). "Furthermore, patients with Gitelman syndrome did not have high PTH levels, while they often had hypophosphatemia and renal phosphate wasting." (PMID 35137195, 2022). "This clinical concern is exacerbated by the lack of consensus on if or how to treat FGF23-mediated hypophosphatemia, as treatment with phosphate supplementation can be counterproductive due to increased parathyroid hormone that may worsen FGF23-mediated urinary phosphate excretion." (PMID 40244590, 2025).
Hypertension (241 papers, 2009 to 2026). The presence of chronic increased pressure in the systemic arterial system. "Parathyroid hormone (PTH) excess is associated with hypertension while elevated PTH has been observed in primary aldosteronism (PA)." (PMID 40608198, 2025). "This meta-analysis, involving 51,234 participants, showed a linear and positive correlation between PTH and hypertension, each 10 pg/ml increase in PTH concentration was associated with a 5% increase in the risk of hypertension (OR, 1.05, 95% CI: 1.02–1.08)." (PMID 38172768, 2024). "The results showed a positive relationship between PTH and the risk of hypertension (OR,1.24, 95% CI: 1.16–1.33)." (PMID 38172768, 2024). "Of these studies, eight (five cohort and three cross-sectional) studies investigated the association of PTH with hypertension; five (two cohort and three cross-sectional) studies assessed the association of PTH with T2D." (PMID 38172768, 2024). "Eight studies with 9135 cases and 28,433 individuals assessed the association between PTH and risk of hypertension." (PMID 38172768, 2024). "Third, we analyzed the association between PTH and hypertension and T2D from different aspects, involving the highest versus lowest PTH meta-analysis and linear dose-response meta-analysis." (PMID 38172768, 2024). "Nevertheless, no comprehensive assessment of the quantitative dose–response association between PTH and hypertension and T2D risk has been reported." (PMID 38172768, 2024). "Although elevated levels of PTH have been associated with hypertension, paradoxically, PTH also exhibits vasodilatory and natriuretic effects." (PMID 38891922, 2024). "The results showed a positive linear correlation between PTH level and hypertension risk (Pnonlinearity =0.222)." (PMID 38172768, 2024). "Nonetheless, a rapid progression of the mineralization process has been attributed to a series of independent risk factors: elevated PTH, hypertension and osteoporosis." (PMID 38785509, 2024). "In the dose-response analysis, the risk of hypertension increased 5% for every 10 pg/ml increase in PTH (OR,1.05, 95% CI: 1.02–1.08)." (PMID 38172768, 2024). "Meanwhile, several cohort and cross-sectional studies also found a positive association between PTH and the risk of hypertension, the results from our linear model examining hypertension risk suggest likewise." (PMID 38172768, 2024). "Elevated levels of parathyroid hormone are associatedwith an increased risk of death from hypertension and cardiovascular events.Insufficient dialysis or reduced glomerular filtration rate (eGFR) can lead tohyperphosphatemia." (PMID 39076321, 2024). "The results acquired were aligned with a former meta-analysis, which also found a positive association between PTH concentration and the risk of hypertension." (PMID 38172768, 2024). "With each 10 pg/ml increase in PTH concentration, the risk of hypertension was increased 5% (OR, 1.05, 95% CI: 1.02–1.08, I2 = 79.6%, Pheterogeneity<0.001)." (PMID 38172768, 2024). "Hypertension is associated with increased levels of various hormones, such as parathyroid hormone, which plays a key role in bone remodeling." (PMID 37397722, 2023). "The results of numerous studies have indicated that PTH promotes Ca2+ entry into cells, increasing vasoconstriction and causing arterial hypertension." (PMID 36389124, 2022). "In an American sample with 3002 participants, higher serum PTH levels were significantly associated with a greater risk of incident hypertension." (PMID 34946242, 2021). "Cross-sectionally, lower 25(OH)D and higher PTH were independently associated with higher prevalence of hypertension [odds ratio (OR) = 0.79; 95% confidence interval (CI): 0.72–0.87 and OR = 1.55; 95% CI: 1.39–1.73] among white women only." (PMID 34531372, 2021). "Hypertension is thought to be linked to bone health through chronic elevation in the levels of parathyroid hormone (PTH), angiotensin II, and catecholamines including adrenaline." (PMID 34128860, 2021).
Hypertension (continued). "In a meta-analysis, circulating PTH levels were associated with a higher risk of arterial hypertension." (PMID 34946242, 2021). "Although the crude results suggested that hypertension and PTH level were significantly associated with BMD improvement, these results were not significant after adjustments for potential confounders." (PMID 32928178, 2020). "The results of this study suggest the potential association of hypertension and PTH level with postoperative BMD improvement." (PMID 32928178, 2020). "Long-standing high levels of PTH, such as in hyperparathyroidism, are frequently related to hypertension, whereas parathyroidectomy is associated with a decrease in [Ca2+]i and blood pressure." (PMID 31109099, 2019). "To date, there is evidence supporting a disordered renin–angiotensin aldosterone system, altered calcium and phosphate metabolism (causing high levels of fibroblast growth factor 23 and parathyroid hormone) and hypertension." (PMID 29024966, 2018). "Both low serum 25(OH)D and high PTH levels are related to arterial stiffness and vascular dysfunction, which are significant elements of hypertension and CVD risk." (PMID 28241878, 2017). "Observational studies have shown that higher PTH levels are independently associated with higher blood pressure and increased risk for incident hypertension, cardiovascular mortality, and structural cardiac dysfunction." (PMID 28808443, 2017). "The possible association between PTH and metabolic dysregulation was explained by IR, high blood pressure, hyperglycemia, and dyslipidemia." (PMID 28384340, 2017). "The high level of PTH causes elevated blood pressure and cardiac contractility, which contributes to myocardial dysfunction, arterial hypertension, and heart failure." (PMID 27763496, 2016). "Higher PTH concentrations were associated with several cardiovascular risk factors, including hypertension and arterial stiffness." (PMID 26000280, 2015). "In the Longitudinal Ageing Study Amsterdam, higher levels of PTH were significantly associated with higher systolic and diastolic blood pressure and higher prevalence of hypertension." (PMID 22937036, 2012). "Several studies have consistently demonstrated that higher levels of circulating PTH were associated with higher blood pressure or prevalence of hypertension." (PMID 22937036, 2012). "We conducted this cross-sectional study to evaluate the associations of serum 25(OH)D and serum PTH with blood pressure and the risk of hypertension in a Chinese population." (PMID 22937036, 2012). "It causes an increase in parathyroid hormone, which increases insulin resistance and is associated with diabetes, hypertension, inflammation, and increased cardiovascular risk." (PMID 23346457, 2012). "Animal and epidemiological studies have shown that high blood pressure is associated with abnormal calcium metabolism, including an increase in urinary calcium excretion, a raised parathyroid hormone level and a tendency for low serum ionized calcium levels." (PMID 21845073, 2011). "Animal and epidemiological studies demonstrate that high blood pressure is associated with increased calcium loss, elevated parathyroid hormone, and increased calcium movement from bone." (PMID 21845073, 2011). "Low vitamin D status is associated with secondary elevation of PTH as well as increased arterial resistance leading to hypertension." (PMID 20049157, 2010). "Primary HPT with an inappropriately elevated PTH level has been shown to be associated with hypertension (in up to 40% of cases) but the mechanism of developing hypertension has remained controversial." (PMID 20049157, 2010). "The present study was conducted to examine the association of hypertension and elevated intact parathyroid hormone in LVH and to evaluate their synergetic effect as risk factors for LVH in hemodialysis patients without other major risk factors." (PMID 20535251, 2009). "We found a linear association between PTH and hypertension (Pnon−linearity= 0.222)." (PMID 38172768, 2024).
Hypertension (continued). "Therefore, we performed a systematic review and meta-analysis of all available data from cross-sectional and cohort studies on the dose–response association of PTH and risk of hypertension and T2D." (PMID 38172768, 2024). "Elevated PTH is associated with an increased risk of hypertension." (PMID 38172768, 2024). "This meta-analysis suggests that higher PTH concentrations might play a role in the pathogenesis of developing hypertension, these associations may underlie the increased risk for cardiovascular disease among participants with high PTH." (PMID 38172768, 2024). "In addition to its well-known role in calcium metabolism, high PTH levels have been shown to increase many cardiovascular risk factors along with hypertension." (PMID 34946242, 2021). "The chronic infusion of PTH has been associated with arterial hypertension." (PMID 31109099, 2019). "Interestingly, higher PTH has been associated with the development of hypertension because of its effects on vascular smooth muscle cells, increasing vascular tone and arterial blood pressure." (PMID 31295336, 2019). "Interestingly, OPG turned out to be associated with a larger AUC than that of hypertension, but similar to that of PTH." (PMID 28683789, 2017). "The cardiovascular effects of vitamin D may be mediated through the PTH axis and linked to reduced concentrations of serum ionized calcium, especially in low-renin human hypertension prevalent among African Americans." (PMID 25505940, 2014). "We hypothesized that lower levels of vitamin D and higher levels of PTH are associated with blood pressure and the risk of hypertension in Chinese." (PMID 22937036, 2012). "One unit increments of natural log of PTH levels were significantly associated with risk of hypertension in the crude model (OR = 1.78, 95% confidence interval 1.38–2.28, P<0.0001) and model adjusted for age and sex (OR = 1.41, 95% confidence interval 1.08–1.83, P = 0.01)." (PMID 22937036, 2012). "In addition, some studies showing a significant association between vitamin D and risk of hypertension fail to adjust for serum parathyroid hormone (PTH), an important calcium-regulating hormone." (PMID 22937036, 2012). "Reduced parathyroid hormone levels are independently associated with blood pressure and the presence of hypertension or pre-hypertension, suggesting that perchlorate may affect blood pressure through its impact on parathyroid hormone secretion, thereby indirectly influencing the aging process." (PMID 40171432, 2025). "Third, PTH may promote vascular calcification and decrease the compliance of vessels, causing the important cushioning function of these arteries to be lost, which is known to result in increased pulse pressure and eventually induces hypertension." (PMID 38172768, 2024). "How parathyroid hormone causes hypertension may be related to the following mechanisms." (PMID 38172768, 2024). "Taken together, collective evidence supports physiological differences between whites and blacks in altered vitamin D/PTH endocrine system and may explain at least in part the racial differences in hypertension and other cardiometabolic disorders associated with 25(OH)D and PTH." (PMID 34531372, 2021). "Individually, lower 25(OH)D or higher PTH level was associated with greater prevalence of obesity and the composite endpoint across racial/ethnic groups, whereas their independent associations with hypertension were statistically significant in white women only." (PMID 34531372, 2021). "In addition, a meta-analysis with six prospective cohort studies, involving a total of 18,994 participants, showed that increased levels of PTH may be associated with a higher risk of hypertension." (PMID 32192220, 2020).